IL1RN (interleukin 1 receptor antagonist)
Description:
Anti-inflammatory antagonist of interleukin-1 family of proinflammatory cytokines such as interleukin-1beta/IL1B and interleukin-1alpha/IL1A. Protects from immune dysregulation and uncontrolled systemic inflammation triggered by IL1 for a range of innate stimulatory agents such as pathogens.
Synonyms: IL-1RN; IL-1ra; IRAP; IL1F3; IL1RA; ICIL-1RA; MGC10430; CRMO2; DIRA; IL-1ra3; MVCD4
Tractability: Small molecule: a high-quality ligand is known. Antibody: UniProt places it where antibodies can reach, with high confidence; its Gene Ontology location is reachable by antibodies, with high confidence; UniProt predicts a signal peptide or a membrane-spanning region. PROTAC: a small molecule that binds it is known.
Gene: Protein-coding gene on chromosome 2 (113,099,315 to 113,134,016, forward strand). Ensembl gene ENSG00000136689.
Subcellular location: Secreted (Isoform 1); Cytoplasm (Isoform 2); Cytoplasm (Isoform 3); Cytoplasm (Isoform 4)
Subcellular location (Human Protein Atlas): Cytosol; Nucleoplasm; Centrosome; Predicted to be secreted
Pathways (Reactome):
Immune System: Interleukin-1 signaling; Interleukin-10 signaling
Gene Ontology:
Molecular function: interleukin-1 receptor antagonist activity; interleukin-1 type I receptor antagonist activity; interleukin-1 type II receptor antagonist activity; interleukin-1, type I receptor binding; interleukin-1, type II receptor binding; protein binding; cytokine activity; interleukin-1 receptor binding
Biological process: negative regulation of heterotypic cell-cell adhesion; negative regulation of interleukin-1-mediated signaling pathway; response to glucocorticoid; immune response; inflammatory response; negative regulation of inflammatory response; signal transduction
Cellular component: cytosol; extracellular exosome; extracellular region; plasma membrane; cytoplasm; vesicle
Genetic constraint (gnomAD): Loss-of-function variants: 7 observed, 8.61 expected, observed/expected ratio (o/e) 0.81, 90% interval 0.46 to 1.51. That is too few expected variants to judge how well the gene tolerates losing a copy. Missense variants: 186 observed, 203.3 expected, observed/expected ratio (o/e) 0.91, 90% interval 0.81 to 1.03. Synonymous variants: 87 observed, 74.16 expected, observed/expected ratio (o/e) 1.17, 90% interval 0.99 to 1.4.
Homologues: Orthologues: chimpanzee IL1RN (88% identical), macaque IL1RN (86% identical), dog IL1RN (79% identical), mouse Il1rn (76% identical), rabbit IL1RN (72% identical), guinea pig IL1RN (67% identical), rat Il1rn (66% identical), zebrafish il1b (20% identical), zebrafish il1fma (20% identical). Paralogues in human: IL36RN (40% identical), IL1F10 (33% identical), IL1B (25% identical), IL36G (25% identical), IL36A (25% identical), IL36B (25% identical), IL37 (24% identical).
Diseases named in the same sentence as IL1RN in open-access papers:
IL1RN is named in the same sentence as 238 diseases in open-access papers, as found by Europe PMC text mining. Sharing a sentence is not in itself a finding about the gene and the disease. The quoted sentences say what the papers report.
COVID-19 (31 papers, 2020 to 2026). A disease caused by infection with severe acute respiratory syndrome coronavirus 2. "Here, we describe severe COVID-19 to associate with autoantibodies against interleukin-1 receptor antagonist (IL-1Ra) and progranulin (PGRN), endogenous antagonists of IL-1 and TNF signaling, respectively." (PMID 42204159, 2026). "The anti-inflammatory interleukin 1 receptor antagonist (IL1RN) signature was down-regulated, with reduced IL1RN recently associated with increased COVID-19 severity." (PMID 38803494, 2024). "On the other hand, those COVID-19 patients with the CC genotype at IL1RN associated with a significantly higher risk of mortality, but this latter association disappears when they are treated with Tocilizumab." (PMID 39346556, 2024). "For the severity COVID-19 predictive mixed model the variables included were sex, body mass index (BMI), presence of comorbidities, and the genetic variants rs2232354, rs11385942 and rs1819040, belonging to the genes IL1RN, LZTFL1 and KANSL1, respectively." (PMID 38605121, 2024). "Furthermore, single nucleotide polymorphisms located in IL1RN are associated with COVID-19 severity, and S100A8/A9 appear to be a potential progression biomarker." (PMID 36230912, 2022). "Significant upregulation of IL1RN and SOCS3, both of which encode cytokine signaling antagonists and contribute to the negative feedback loops, were observed in the BALF cells from COVID-19 patients (n = 8)." (PMID 33912590, 2021). "The majority of patients had a history of lower respiratory tract infection before COVID-19 (89.4%, except for two patients with STK4 and IL1RN deficiencies)." (PMID 33263173, 2021). "IL1RN modulates the COVID-19 cytokine release syndrome via endogenous “anti-inflammatory” pathways." (PMID 38543303, 2024). "Specifically, the results of the current study show that the presence of the CC genotype at IL1RN polymorphism associates with an increased risk of mortality in severe COVID-19 patients that are not treated with Tocilizumab." (PMID 39346556, 2024). "A review study observed that variants in cytokine genes such as IL-1β, IL1R1, IL1RN, IL-6, IL-17A, FCGR2A, and TNF may be associated with disease susceptibility and/or severity, cytokine storm, and/or COVID-19 complications like thrombosis." (PMID 37662953, 2023). "Variants in cytokine genes such as IL1B, IL1R1, IL1RN, IL6, IL17A, FCGR2A, and TNF could be related to disease susceptibility and cytokine storm, and/or COVID-19 complications (e.g., venous thrombosis)." (PMID 33868239, 2021). "Previous studies reported that COVID-19 is frequently associated with a massive production of 14 cytokines including IFN-γ, IL-1RA (IL1RN), IL-2RA, IL-6, IL-10, IL-18, HGF, MCP-3 (CCL7), MIG (CXCL9), M-CSF (CSF1), G-CSF (CSF3), MIG-1a (CCL3), CTACK (CCL27), and IP-10 (CXCL10)." (PMID 34262555, 2021). "In post-COVID-19 patients, we observed co-upregulation of groups of related red module proteins such as the CXCR3 chemokines (CXCL9, CXCL10, and CXCL11), and interleukin-1A (IL1A) and its antagonist IL1RN." (PMID 35151371, 2022). "Besides chemokines, interleukin genes, such as IL1RN and IL1B, were also significantly upregulated in COVID-19 patients." (PMID 33912590, 2021). "Moreover, the roles of anti-inflammatory cytokines in COVID-19 pathogenesis, including IL1R2, IL1RN, IL10, and TGFB1, are unclear and should be investigated in the future." (PMID 33101705, 2020). "Therefore, our data indicated that genes such as Il1b, S100a, Il1rn and other inflammatory factors which were highly expressed by CD14+ monocytes, may be the main contributors to the cytokine storm in COVID-19." (PMID 36817436, 2023).
COVID-19 (continued). "The interleukin genes IL1RN and IL27 were only upregulated in G2; however, IL6 was not upregulated in either group, corroborating previous observations in lung tissue, despite high levels in the blood of COVID-19 patients." (PMID 35438176, 2022).
Arthritis (22 papers, 2010 to 2022). Inflammation of a joint. "We previously presented S100A8/A9 as a good biomarker for joint inflammation and arthritis pathology under circumstances of high IL-1 signaling in mice that lack the gene encoding IL-1 receptor antagonist (Il1rn−/− mice)." (PMID 34412663, 2021). "CCR2+Vγ6+ γδ17 T cells played a pathogenic role in IL-1Ra-deficient (Il1rn–/–) mice, an IL-17-dependent spontaneous arthritis murine model." (PMID 33072104, 2020). "IL1rn knockout (IL1rn−/−) mice are susceptible to a variety of autoimmune diseases including arthritis, psoriasis, diabetes, and encephalomyelitis." (PMID 28645307, 2017). "We show that the aberrant microbiota in IL1rn−/− mice have the capacity to enhance LP Th17 cells which are associated with arthritis, likely via TLR4-induced production of IL-1β, IL-6, and IL-23." (PMID 28645307, 2017). "The decreased Barnesiella in IL1rn−/− mice is consistent with a previous study associating the abundance of Barnesiella with resistance to arthritis in HLA-DRB1*0402 mice." (PMID 28645307, 2017). "This suggests that additional (genetic) susceptibility of the host, as in IL1rn−/− mice, is required for the development of arthritis." (PMID 28645307, 2017). "For example, it inhibits the development of arthritis in mice deficient in the interleukin receptor antagonist (IL1RN)." (PMID 23533776, 2013). "While γδ17 and Th17 cells may have complementary pathogenic roles in the development of IL1rn−/− arthritis, our data suggest that IL-17-producing cells located in lamina propria and induced by IL1rn−/− intestinal microbiota are TCRβ-expressing CD4+ Th17 cells." (PMID 28645307, 2017). "We investigated the role of interleukin-1 receptor antagonist (IL-1Ra) in regulation of commensal intestinal microbiota, and assessed the involvement of microbiota subsets and innate and adaptive mucosal immune responses that underlie the development of spontaneous arthritis in Il1rn−/− mice." (PMID 28645307, 2017). "Indeed, IL-1 receptor antagonist or Anakinra (Kineret) is an FDA-approved treatment for human rheumatoid arthritis and Il1rn deficiency in mice results in spontaneous polyarthropathies." (PMID 29216931, 2017). "In addition, IL-1 receptor(R) antagonist (a)-deficient (Il1rn-/-) mice spontaneously develop arthritis in an IL-17- and T-cell dependent manner suggesting that excess IL-1 signaling caused by IL-1Ra deficiency induces IL-17 production from T cells and the development of arthritis." (PMID 32085540, 2020). "Macroscopically scored arthritis severity was comparable between Il1rn−/− and Il1rn−/−XS100a9−/− mice." (PMID 34412663, 2021). "Nevertheless, arthritis development was induced on monocontamination of GF IL1rn−/− mice with Lactobacillus bifidus." (PMID 34576825, 2021). "Selective antibiotic treatment revealed that tobramycin-induced alterations of commensal intestinal microbiota, i.e., reduced Helicobacter, Flexispira, Clostridium, and Dehalobacterium, suppressed arthritis in IL1rn−/− mice." (PMID 28645307, 2017). "The arthritis phenotype in IL1rn−/− mice was previously shown to depend on Toll-like receptor 4 (TLR4)." (PMID 28645307, 2017). "When cultured ex vivo with PMA and ionomycin, SI-LP cells from IL1rn−/−Tlr4−/− mice produced significantly less IL-17 compared with cells from IL1rn−/−Tlr4+/+ mice before the onset of arthritis (P = 0.0028)." (PMID 28645307, 2017). "We also showed that IL1rn−/− arthritis is dependent on the activation of Toll-like receptor 4 (TLR4), which affected systemic Th17 cell differentiation." (PMID 28645307, 2017). "Considering differential roles of TLR2 and TLR4 in IL1rn−/− arthritis, we sequenced samples of IL1rn−/−Tlr2−/− and IL1rn−/−Tlr4−/− mice in parallel." (PMID 28645307, 2017). "Together, these observations suggest an essential role for TLR4 in the induction of intestinal LP IL-17 production associated with extra-intestinal IL-17 levels and the development of arthritis in IL1rn−/− mice." (PMID 28645307, 2017).
Arthritis (continued). "Our previous studies showed that IL1rn−/−Tlr2−/− mice develop a more severe arthritis compared with IL1rn−/− mice." (PMID 28645307, 2017). "Here we showed that both CD4+ T cells and γδ17 cells are important for development of arthritis in Il1rn−/− mice, because antibody-mediated depletion of either γδ T or CD4+ T cells suppressed the development of arthritis." (PMID 26108163, 2015). "Since our collagen-induced arthritis model is different from the Il1rn-dependent model in which polyarthritis develops spontaneously, it is difficult to compare directly which therapeutic method, anti-IL-17A or anti-CXCR2 is more effective." (PMID 21991368, 2011). "An imbalance of IL-1β and IL1-RN signalling has been proposed as an important factor in several inflammatory conditions in man such as asthma and arthritis." (PMID 20670446, 2010). "Indeed, depletion of monocytes using clodronate liposomes suppressed the development of splenomegaly and arthritis in IL1rn−/− mice." (PMID 36443301, 2022). "Specifically, in the spontaneous IL-1rn−/− mouse model of autoimmune arthritis, TLR4 signaling by the microbiome appears to be responsible for the induction of arthritis, as germ-free IL1rn−/− mice or conventional IL-1rn−/− TLR4−/− mice are protected from autoimmune arthritis." (PMID 33810172, 2021). "However, in the Tlr4−/−Il1rn−/− mouse model, the arthritis manifestation is weaker than that of the Il1rn−/− mouse model." (PMID 32153586, 2020). "In addition, transfer of conventional IL1rn−/− microbiota to GF IL1rn−/− mice re-induced arthritis and resulted in a severe disease comparable to that in conventional IL1rn−/− mice." (PMID 28645307, 2017). "We previously showed that IL1rn−/−Tlr4−/− mice have a marked and sustained reduction of arthritis." (PMID 28645307, 2017). "To determine whether the increase in intestinal Th17 cells and spontaneous arthritis in IL1rn−/− mice depends on commensal microbiota, we established GF IL1rn−/− mice." (PMID 28645307, 2017). "Although IL1rn−/− intestinal microbiota do not cause arthritis in a normal (WT) host, these microbiota, in particular tobramycin-sensitive bacteria, contribute to the development of arthritis in IL1rn−/− mice." (PMID 28645307, 2017). "Il1rn−/− γδ T cells induced arthritis upon transfer into scid/scid mice." (PMID 26108163, 2015). "Therefore, our results show that CD4+ T cells direct the tissue specificity of inflammation, and γδ17 cell-derived IL-17 elicits local inflammation and arthritis in Il1rn−/− mice." (PMID 26108163, 2015). "Interestingly, Fcer1g, Fcgr3 are both show a correlation with gene expression of Il1rn as well as differential expression between spontaneous arthritis mice and healthy BALB/c mice." (PMID 25488730, 2014). "In addition, acute stimulation of TLRs, which are primarily contained in the innate immune response to microbial pathogens, by a TLR2 agonist, Pam3Cys, could aggravate the severity in IL1rn−/− arthritis mice." (PMID 34576825, 2021). "Given that additional TLR2 deficiency did not affect the microbiota of IL1rn−/− mice to a major extent, we speculate that severe arthritis in IL1rn−/−Tlr2−/− mice is due to the altered host immune response, specifically reduced function of Treg cells, rather than alteration in the microbiome." (PMID 28645307, 2017). "Supporting this hypothesis, the pathology of IL1rn deficiency and CpG-induced MAS was largely abrogated by rapamycin treatment while unrestricted activation of mTORC1 in Tsc2 KO mice was sufficient to elicit an SD-like syndrome, including both arthritis and fulminant MAS." (PMID 36443301, 2022). "Among the microbiota increased in IL1rn−/− mice, Streptococcus species are known inducers of chronic TLR-mediated arthritis in animal models when injected intra-articularly." (PMID 28645307, 2017).
Arthritis (continued). "We found that scid/scid mice that received transfer of whole-Il1rn−/− T cells or a mixture of γδ and CD4+ T cells developed arthritis, whereas those that received transfer of γδ or CD4+ T cells alone did not." (PMID 26108163, 2015). "These experiments revealed that although SFB were able to exacerbate arthritis in IL1rn−/− mice, only tobramycin but not vancomycin significantly diminished arthritis." (PMID 28645307, 2017). "While IL-1 receptor antagonist knock-out (Il1rn–/–) mice (spontaneously develop autoimmune arthritis) do not get arthritis under germ-free conditions, mono-colonization of Lactobacillus bifidus with Il1rn–/– mice resulted in rapid onset of arthritis." (PMID 27011180, 2016). "Therefore, IL1rn−/− commensal microbiota, although not sufficient to induce arthritis in a WT host, are critical for the full development of arthritis in IL1rn−/− mice." (PMID 28645307, 2017). "However, GF Il1rn−/− mice, manifested no spontaneous arthritis symptoms, which strongly indicated that gut microbiota could somehow induce the inflammation reaction." (PMID 32153586, 2020).
gastric cancer (14 papers, 2007 to 2024). A primary or metastatic malignant neoplasm involving the stomach. "Consistent with multifactorial pathogenesis, smoking, alcohol use, high red meat or processed meat consumption, excess salt intake, and carriage of IL1RN*2 were each associated with a modest increase in gastric cancer risk." (PMID 37849565, 2023). "Among 10 SNPs genotypes, variant genotypes of rs9005 in 3’ UTR regions of Interleukin 1 Receptor Antagonist (IL-1RN) consisting of G.A. heterozygous genotype and A.A. homozygous genotype were associated with a high risk of gastric cancer." (PMID 35330456, 2022). "Genetic alterations and polymorphisms in the IL1RN gene have been associated with an increased risk for developing different malignancies, including gastric cancer, prostate cancer, and UCB." (PMID 25114677, 2014). "IL1RN*2 was also associated with an increased risk of gastric cancer among Caucasians (OR: 1.30, 95 % CI: 1.09–1.54)." (PMID 23995914, 2013). "Pro-inflammatory IL1B and IL1RN polymorphisms are associated with increased risk of gastric carcinoma in Caucasian populations." (PMID 18842150, 2008). "In view of the inflammatory nature of cancer cachexia, we determined the predictive value of IL-1B-31 T/C, -511 C/T, +3954 C/T and IL-1RN VNTR gene polymorphisms on the occurrence of cachexia associated with locally advanced gastric cancer." (PMID 17359523, 2007). "Working from assumption of substantial inflammatory contribution to cancer cachexia, we hypothesized that IL-1B-31 T/C, -511 C/T, +3954 C/T and IL-1RN gene polymorphisms have some relationship with the development of cachexia associated with locally advanced gastric cancer." (PMID 17359523, 2007). "Our results were consistent with those of previous reports on the upregulation of IL1RN in cervical carcinoma, gastric cancer, lung cancer, and endometrial cancer tissues." (PMID 33238942, 2020). "IL1RN has been studied in several cancers, including prostate carcinoma, cervical carcinoma, gastric carcinoma, bronchogenic carcinoma, endometrial cancer, lung cancer, ovarian cancer, oral malignancies, leukemia, and other cancers." (PMID 33238942, 2020). "Polymorphisms in genes encoding pro-inflammatory cytokines have shown to increase the risk of gastric cancer, specifically interleukin-1β (IL1B-511/31, interleukin-1 receptor antagonist (IL1RN*2), and tumour necrosis factor A (TNFA-308)." (PMID 26186918, 2015). "The summary OR of gastric cancer risk associated with IL1B–511T, 231C, 13954T and IL1RN*2 was 1.26 (95 % CI: 1.03–1.55), 1.00 (95 % CI: 0.82–1.22), 1.37 (95 % CI: 0.94–2.00) and 1.20 (95 % CI: 1.01–1.41), respectively." (PMID 23995914, 2013). "Among the host factors, cytokine gene polymorphisms were shown to increase the risk of gastric cancer, specifically IL1B-31, IL1RN, and TNFA-307 single nucleotide polymorphisms in European populations, and IL1RN in a Brazilian population." (PMID 21435255, 2011). "A study of gastric carcinoma pointed out that on the one hand, IL1RN may promote tumor growth via the impairment of cellular immunity; on the other hand, IL1RN enables malignant cells to escape host immune responses." (PMID 33238942, 2020). "In this meta-analysis IL1B −511T allele and IL1RN*2 variable number of tandem repeats (VNTR) are significantly associated with an increased risk of developing gastric carcinoma and even more significantly with non-cardia gastric carcinoma or with intestinal type gastric carcinoma." (PMID 23995914, 2013). "We found that immune related genes such as TLR8, Interleukin-7 (IL-7), Leptin (LEP), IL1RN had intimate relationships with AQP9 expression in breast, colon, lung and gastric cancers." (PMID 33247170, 2020).